FAT1 (FAT atypical cadherin 1)
Diseases named in the same sentence as FAT1 in open-access papers (continued):
Sharing a sentence is not in itself a finding about the gene and the disease.
head and neck squamous cell carcinoma (continued). "Owing to the importance of FAT1 in organisms, mutations in FAT1 may cause diverse malignant biological behaviors and have been detected in multiple diseases, such as acute lymphoblastic leukemia, hepatocellular carcinoma, pituitary spindle cell tumors, and head and neck squamous cell carcinoma." (PMID 40416971, 2025). "FAT1 is mutated in glioblastoma and human squamous cell carcinoma (HSCC), including nearly 30% of head and neck squamous cell carcinoma (HNSCC) cases." (PMID 37835395, 2023). "Its highest mutation rate is found in head and neck squamous cell carcinoma (HNSCC), in which FAT1 is the second most frequently mutated gene." (PMID 35965328, 2022). "Analysis of large tissue collections revealed YAP activation in most head and neck squamous cell carcinoma (HNSCC), but only 29.8% of HNSCC cases present genetic alterations in the FAT1 tumor suppressor gene that may underlie persistent YAP signaling." (PMID 34725466, 2021). "The FAT1 alterations occur in 29.8% of head and neck squamous cell carcinoma (HNSCC), and FAT1 functional loss results in YAP1 activation." (PMID 33420124, 2021). "Genes CASP8 and FAT1 are reported to co-occur in TCGA-Head and Neck Squamous Cell Carcinoma; however, we observe similar incident in only one out of 11 samples with these SNVs." (PMID 34136393, 2021). "As described in head and neck squamous cell carcinoma, FAT1 assembles a multimeric Hippo signaling complex resulting in the activation of core Hippo kinases." (PMID 31028364, 2020). "We examined the clinical significance of FAT1 in head and neck squamous cell carcinoma (HNSCC) using four publicly available HNSCC cohorts and one HNSCC cohort enrolled at a tertiary medical center." (PMID 34939311, 2022). "FAT1‐HR, FAT1‐associated high risk; FAT1‐LR, FAT1‐associated low risk; FHCRC, Fred Hutchinson Cancer Research Center; HNSCC, head and neck squamous cell carcinoma; KHUMC, Kyung Hee University Medical Center; MDACC, MD Anderson Cancer Center; NA, not available; TCGA, The Cancer Genome Atlas." (PMID 34939311, 2022). "By focusing on head and neck squamous cell carcinoma (HNSCC), which displays frequent FAT1 alterations (29.8%), we provide evidence that FAT1 functional loss results in YAP1 activation." (PMID 29985391, 2018). "In head and neck squamous cell carcinoma (HNSCC), use of SW-682 to block YAP/TAZ-TEAD binding led to an antitumor response in FAT1-mutant HNSCC xenograft models." (PMID 41347094, 2025).
squamous cell carcinoma (24 papers, 2018 to 2025). A carcinoma arising from squamous epithelial cells. "Additional research indicates that in squamous cell carcinoma, the loss of FAT1 function facilitates tumor initiation, progression, invasiveness, stemness, and metastasis by triggering a hybrid state of EMT." (PMID 40093514, 2025). "Although currently untargetable, FAT1 mutations have been implicated in resistance to epidermal growth factor inhibitors in squamous cell carcinomas." (PMID 41296436, 2025). "Later sequencing evidence revealed somatic mutations associated with FAT1 inactivation, particularly in squamous cell carcinomas arising at different body sites 20-22." (PMID 40083689, 2025). "Elevation of circRNA FAT1 (circFAT1) in squamous cell carcinoma (SCC) combines and controls the positive association between tumor stemness and immune evasion by stimulating the expression of STAT3 (signal transducer and activator of transcription 3)." (PMID 38329551, 2024). "FAT1 encodes a protocaladherin, which is very frequently mutated in many human cancers, especially squamous cell carcinomas (SCCs)." (PMID 35646054, 2022). "The mutations in FAT1 gene were detected frequently in diverse cancers, particularly in squamous cell carcinomas, potentially serving as an oncogene or a tumor suppressor." (PMID 36076209, 2022). "In mouse and human squamous cell carcinomas, the loss of FAT1 function can promote tumorigenesis by inducing a mixed EMT state." (PMID 36506331, 2022). "Here, it is reported that elevated circular RNA FAT1 (circFAT1) in squamous cell carcinoma (SCC) unifies and regulates the positive association between cancer stemness and immune evasion by promoting STAT3 activation." (PMID 34258151, 2021). "Recurrent somatic variants of FAT1 have been identified in several cancers and particularly in squamous cell carcinomas." (PMID 29416628, 2018). "Gene mutations in cancer cells may promote a hybrid EMT phenotype; for example, this hybrid EMT state is observed in FAT atypical cadherin 1 (FAT1)-mutated human squamous cell carcinomas." (PMID 41368628, 2025). "FAT1 mutations are the most common in squamous cell carcinoma, especially OSCC (30–40%) (2013)." (PMID 38293699, 2023). "Recent studies on squamous cell carcinoma of mice and humans have revealed that the loss of function of FAT1 leads to an epithelial-mesenchymal hybrid transition phenotype, which, in turn, promotes tumor initiation, progression, invasiveness, stemness and metastasis." (PMID 34202629, 2021). "Recent advancements in next‐generation sequencing (NGS) have revealed that mutations in the FAT1 gene and the subsequent activation of the Wnt/β‐catenin signaling pathway may contribute to chemoresistance in well‐differentiated squamous cell carcinoma compared to poorly differentiated tumors." (PMID 39101462, 2024). "Loss of FAT1 function induces a mixed EMT state in human and animal squamous cell carcinomas, which enhances carcinogenesis, progression, invasiveness, stemness, and metastasis." (PMID 40661938, 2025). "In mouse and human squamous cell carcinoma, FAT1 promotes tumor initiation, progression, invasiveness, stemness and metastasis." (PMID 37147285, 2023). "FAT1 was detected mainly in the cytoplasm of squamous carcinoma cell (weak staining in the region of squamous pearl formation), and normal oral mucosa specimens displayed positivity mainly in sporadic cells of basal layers." (PMID 35646625, 2022). "Recently, it has been confirmed that the loss of FAT1 function promotes tumorigenesis, development, invasion, and metastasis by inducing mixed epithelial-to-mesenchymal transition (EMT) status in human squamous cell carcinoma." (PMID 35646054, 2022). "Lastly, given FAT1 deletion has been reported to promote cancer stem cells (CSCs) in squamous carcinomas 23, we further looked at whether altered FAT1 levels in TNBC also affects tumor stemness." (PMID 40083689, 2025).
squamous cell carcinoma (continued). "Furthermore, we examined the expression of FAT1 in the normal epithelial cell lines HIOEC and HaCaT and the HNSCC cell lines HN4, SCC9, SCC25, and CAL27 and found that FAT1 was more highly expressed in normal epithelial cell lines than in squamous carcinoma cell lines." (PMID 39781458, 2025).
lung carcinoma (22 papers, 2011 to 2026). "Our findings unveiled FAT1 overexpression in diverse cancer types, including lung cancer, concomitant with its association with an unfavorable prognosis." (PMID 38855103, 2024). "These collective findings suggest that FAT1 has potential utility both as a biomarker and as a therapeutic target for lung cancer." (PMID 38855103, 2024). "The suppression of FAT1 in lung cancer cells results in reduced cell proliferation, migration, and invasion." (PMID 38855103, 2024). "The authors demonstrated a correlation between multiple genetic alterations, such as aberrant expression of FAT1, deletion of RB1, loss of the long (q) arm of chromosome 5, and lung cancer." (PMID 38539567, 2024). "In the present investigation, we employed bioinformatic analyses, as well as in vitro and in vivo experiments to elucidate the functional significance of FAT1 in pan-cancer, with a primary focus on lung cancer." (PMID 38855103, 2024). "A recent lung cancer transcriptome meta-analysis showed that several HIPPO pathway component (NF2, LATS1, PTPN14, YAP1, TAZ, TAOK, and FAT1) genes were found to fuse in lung carcinoma, and they were independent prognosis factors for low lung cancer survival." (PMID 36147635, 2022). "These gene pairs were distinct across cancer types in general, but some simultaneously occurred in different cancers, e.g., NFATC4/FAT1 appeared in both endometrial and lung cancers and PEG3/ZIM2 appeared in skin and esophageal cancers." (PMID 26212640, 2015). "FAT1 was also found in lung cancer where SGMs were enriched in the tobacco signature SBS4." (PMID 37922356, 2023). "In human lung cancer cells, the increased n-3 PUFA in fat-1-transfected cells resulted in reduced invasive properties due to down regulation of invasion-related genes, MMP-1 and integrin-α2." (PMID 21655218, 2011). "To investigate whether FAT1 alterations drive WGD, we used the PC9 lung cancer model to quantify the proportion of actively replicating cells with >6N genome content (the basal ploidy of PC9 is 3N)." (PMID 39738653, 2024). "In the old lung cancer group, there were genes significantly concurrent with actionable driver genes (CDKN2A, NF1): FAT1, LRP1B, ARID2 with CDKN2A; EPHB1 with NF1, and genes significantly exclusive with actionable driver genes (EGFR, KRAS): MLL2, STK11, KRAS with EGFR." (PMID 35096611, 2021). "Analysis indicated that CDKN2A, FAT1, MSH6, ARID1A, KEAP1, NF1, and SMAD4 mutation was more recurrent in patients with ERBB2 SNV/indels within the kinase domain compared with non-kinase domain in lung cancer." (PMID 35911441, 2022).
melanoma (21 papers, 2011 to 2025). A malignant, usually aggressive tumor composed of atypical, neoplastic melanocytes. "We conducted multiple immunologic analyses and pathways exploration to illuminate the potential mechanisms behind FAT1 mutations in melanoma." (PMID 35739249, 2022). "In the present study, a markedly elevated TMB and MB was observed in FAT1 mutated melanoma and NSCLC patients, which supports the potential ICI predictive roles of FAT1 mutations." (PMID 35739249, 2022). "In the pooled melanoma cohort, univariate survival analysis revealed that patients with FAT1 mutations had a significantly improved ICI prognosis than those wild-type patients (median survival time: 41.9 vs. 25.6 months, Log-rank test P = 0.013)." (PMID 35739249, 2022). "In melanoma, patients with FAT1 mutations had a significantly improved survival outcome than those wild-type patients (HR: 0.67, 95% CI: 0.46–0.97, P = 0.033)." (PMID 35739249, 2022). "We found that a significantly enhanced TMB was enriched in melanoma patients with FAT1 mutations (Wilcoxon rank-sum test P < 0.001)." (PMID 35739249, 2022). "In this study, we curated eight independent melanoma datasets into a pooled cohort and observed that FAT1 mutations were associated with a favorable ICI response and outcome." (PMID 35739249, 2022). "GSEA analysis showed that immune response-related pathways (e.g., interferon α and γ responses) and cell cycle pathways (e.g., G2M checkpoint) were markedly enriched in melanoma patients with FAT1 mutations (all FDR < 0.001)." (PMID 35739249, 2022). "In this study, we observed that patients with FAT1 mutations exhibited a favorable prognosis in melanoma, NSCLC, and pan-cancer cohorts with immunotherapy settings." (PMID 35739249, 2022). "A recent study has reported that FAT1 mutations were associated with favorable ICI treatment efficacy in melanoma and NSCLC patients." (PMID 36497098, 2022). "Molecular profiling confirmed the diagnosis of melanoma and identified mutations in the TERT promoter, NRAS, NF1, PBRM1, FAT1, and ATM genes." (PMID 40125165, 2025). "In summary, by integrating genomic profiles and clinical ICI data, we identified that FAT1 mutations were predictive of ICI response and outcome in melanoma, NSCLC, and pan-cancers." (PMID 35739249, 2022). "We performed multivariable Cox regression models in melanoma and NSCLC cohorts with multiple confounding factors, including RELN and FAT1 mutations, taken into account." (PMID 36497098, 2022). "By using melanoma and NSCLC patients treated with ICIs, we retrospectively investigated the immunotherapy predictive roles of FAT1 mutations." (PMID 35739249, 2022). "Melanoma and NSCLC samples from the Cancer Genome Atlas were used to evaluate the potential immunologic mechanisms of FAT1 mutations." (PMID 35739249, 2022). "By using the same pooled melanoma and NSCLC cohorts, we also discovered other mutations of the genes FAT1, COL3A1, NRAS, NARS2, DCC, and PTPRT were associated with better ICI response and outcome." (PMID 35884556, 2022). "By using somatic mutation and transcriptomic data from TCGA melanoma and NSCLC cohorts, we analyzed the distinct FAT1 expressions in patients with distinct FAT1 mutational types." (PMID 35739249, 2022). "In this study, we retrospectively collected melanoma and NSCLC patients treated by ICIs to explore the association between FAT1 mutations and immunotherapy efficacy." (PMID 35739249, 2022). "Similar results of FAT1 mutations with enhanced TMB and NB were also detected by using the melanoma somatic mutation data in the TCGA cohort (both P < 0.001)." (PMID 35739249, 2022). "Interestingly, somatic mutations in FAT1 have been shown to be positively correlated with high TMB and response to ICI therapy in melanoma and non-small cell lung cancer." (PMID 40248199, 2025).
melanoma (continued). "Similarly, a study based on integrated multi-omics immunotherapy cohorts demonstrated that FAT1 mutations are associated with improved immune checkpoint blockade (ICB) treatment outcomes in both non-small cell lung cancer and melanoma." (PMID 40672387, 2025). "Thus, FAT1 can be recommended as a biomarker for immunotherapy in patients with melanoma and NSCLC24." (PMID 38167455, 2024). "Mutations in FAT1, a gene of Hippo pathway, were associated with higher durable clinical benefit and significantly improved survival outcomes than wild‐type NSCLC patients, same results were also confirmed in melanoma patients and a pan‐cancer cohort." (PMID 38396367, 2024). "FAT atypical cadherin 1 (FAT1), which frequently mutates in melanoma and NSCLC." (PMID 35739249, 2022). "Interestingly, while keratinocytes show predominant localization of FAT1 to cell-cell junctions, melanoma cells exhibit high levels of cytoplasmic FAT1 expression." (PMID 35647082, 2022). "We observed that both mutations exhibited preferable ICI treatment prognoses in melanoma and NSCLC patients after mutually adjusting (all HR < 1, all p < 0.05), which suggests that RELN and FAT1 mutations are two independent biomarkers for predicting ICI response." (PMID 36497098, 2022). "FAT1 up-regulation is an unfavorable prognostic factor for precursor B-cell acute lymphoblastic leukemia patients and recent studies in melanoma and pancreatic cancer have demonstrated that FAT1 undergoes an aberrant processing and an altered localization compared to normal cells." (PMID 30416985, 2018). "Similar findings were observed in melanoma in the Fat-1 transgenic mouse model." (PMID 30213082, 2018). "In addition, the growth of implanted B16 human melanoma cells was markedly reduced in Fat-1 compared to wt mice." (PMID 21655218, 2011). "In melanoma and NSCLC, FAT1 can inhibit the tumor initiation ability of NSCLC cells by activating the Hippo signaling pathway, resulting in a significantly better survival outcome in patients with FAT1 mutations than the wild type and correlating with better immunogenicity and ICI efficacy." (PMID 38167455, 2024). "Results showed no significant expression differences were observed in all comparison subgroups (Wilcoxon test, all P > 0.05), which suggests that FAT1 mutation may not influence its own expression levels in melanoma and NSCLC." (PMID 35739249, 2022). "To establish the broader relevance of this phenomenon, we extended our investigation to the B16F10 melanoma model, in which a similar negative correlation between FAT1 expression and lymphatic vessel density was also observed in tumor-associated lymphatic vessels and normal lymphatic vessels." (PMID 41230499, 2025). "We also evaluated the prognostic roles of FAT1 mutations in melanoma and NSCLC patients treated with distinct chemotherapies from TCGA cohorts; and no significant survival differences were observed between FAT1 mutated and wild-type subgroups in both tumors (Log-rank test, both P > 0.05)." (PMID 35739249, 2022).
glioblastoma (20 papers, 2014 to 2025). The most malignant astrocytic tumor (WHO grade IV). "Somatic mutations in FAT1 result in Wnt activation in multiple types of cancer, including glioblastoma and colorectal cancer." (PMID 25517963, 2014). "Knock down of FAT1 in vitro has also resulted in the reduced expression of STAT1 protein in glioblastoma cell line signifying positive correlation between FAT1 and STAT1." (PMID 37476290, 2023). "This region includes the tumor suppressor FAT1, which was recurrently deleted in colorectal cancers, glioblastoma and HNSCC." (PMID 32617189, 2020). "These authors showed that FAT1 is associated with HIF-1α expression, as well as with its targets PGK1 (Phosphoglycerate kinase 1) and VEGFA in human glioblastoma samples." (PMID 31010154, 2019). "Targeting the NF-κB-FAT1 axis might inhibit the important tumor-promoting pathway in glioblastoma because FAT1 and NF-κB independently enhance protumorigenic inflammation and upregulate the expression of HIF-1α/EMT/stemness in tumors." (PMID 35368876, 2022). "FAT1 knockdown in glioblastoma inhibited all EMT and stemness markers, including OCT-4." (PMID 32429463, 2020). "FAT atypical cadherin 1 (FAT1) promotes glioblastoma (GBM) by promoting protumorigenic inflammatory cytokine expression in tumor cells." (PMID 35720420, 2022). "Previously, we have documented upregulation of FAT1 gene in glioblastoma (GBM) tumors which was found to increase the expression of proinflammatory markers, HIF-1α, stemness genes and EMT markers in glioma cells." (PMID 31992226, 2020). "We have earlier shown the role of FAT1 in promoting epithelial–mesenchymal transition (EMT), invasiveness, hypoxia-activated signaling, stemness, and clonogenicity in glioblastoma (GBM) cells." (PMID 35720420, 2022). "In vitro, they demonstrated that severe hypoxia induces the expression of FAT1 and that the depletion of endogenous FAT1 under hypoxia induces a decrease in HIF-1α, CAIX, GLUT1, VEGFA, MCT4, HK2, BNIP3, and REDD1, as well as a decrease in glioblastoma cell invasion." (PMID 31010154, 2019). "Previous study revealed that FAT1 positively correlated with multiply hypoxia related genes and it was a potent regulator of EMT both via or independent of HIF1a in glioblastoma." (PMID 32677981, 2020).